TNS1 (tensin 1)
Description:
May act as a protein phosphatase and/or a lipid phosphatase (Probable). Involved in fibrillar adhesion formation. Essential for myofibroblast differentiation and myofibroblast-mediated extracellular matrix deposition. Enhances RHOA activation in the presence of DLC1. Plays a role in cell polarization and migration. May be involved in cartilage development and in linking signal transduction pathways to the cytoskeleton.
Synonyms: TNS; DKFZp586K0617; PPP1R155; MST091; MST122; MST127; MSTP091; MSTP122; MSTP127; MXRA6
Tractability: Antibody: UniProt places it where antibodies can reach, with high confidence. PROTAC: ubiquitination databases record sites on it; its protein half-life has been measured.
Gene: Protein-coding gene on chromosome 2 (217,799,588 to 218,033,982, reverse strand). Ensembl gene ENSG00000079308.
Subcellular location: Cell surface; Cell junction, focal adhesion; Cytoplasm, cytoskeleton
Subcellular location (Human Protein Atlas): Focal adhesion sites
Gene Ontology:
Molecular function: protein binding; RNA binding
Biological process: fibroblast migration; cell-matrix adhesion
Cellular component: cell surface; focal adhesion; cytoplasm; cytoskeleton; plasma membrane; plasma membrane bounded cell projection
Genetic constraint (gnomAD): Loss-of-function variants: 51 observed, 144.28 expected, observed/expected ratio (o/e) 0.35, 90% interval 0.28 to 0.45. The upper end of that interval is the gene's LOEUF score, 0.45, which puts it in group 1 of 6, group 1 being the genes least tolerant of losing a copy. Missense variants: 2,096 observed, 2,222.3 expected, observed/expected ratio (o/e) 0.94, 90% interval 0.91 to 0.98. Synonymous variants: 884 observed, 896.95 expected, observed/expected ratio (o/e) 0.99, 90% interval 0.93 to 1.04.
Homologues: Orthologues: macaque TNS1 (98% identical), chimpanzee TNS1 (92% identical), dog TNS1 (92% identical), pig TNS1 (89% identical), mouse Tns1 (88% identical), rat Tns1 (88% identical), rabbit TNS1 (85% identical), guinea pig TNS1 (76% identical), tropical clawed frog tns1 (62% identical), zebrafish tns1b (50% identical). Paralogues in human: TNS3 (36% identical), PTEN (6% identical), TMEM266 (6% identical), TPTE2 (6% identical), TPTE (5% identical), HVCN1 (3% identical).
Diseases named in the same sentence as TNS1 in open-access papers:
TNS1 is named in the same sentence as 79 diseases in open-access papers, as found by Europe PMC text mining. Sharing a sentence is not in itself a finding about the gene and the disease. The quoted sentences say what the papers report.
breast carcinoma (19 papers, 2017 to 2025). "LINC01271 is believed to promote the diagnostic effect of breast cancer by regulating the expression of TNS1, and it is a potential target for breast cancer treatment." (PMID 33585468, 2020). "Furthermore, Kaplan–Meier analyses showed that enhanced TNS1 expression was closely associated with reduced survival in patients with advanced breast cancer." (PMID 36358270, 2022). "Furthermore, Kaplan–Meier (KM) analyses indicate that enhanced expression levels of TNS1 are strongly associated with decreased survival of advanced-stage breast cancer patients." (PMID 32054828, 2020). "For example, TNS1 promotes cell migration in 4T1 breast cancer cells but inhibits invasion of MCF-7, SKBR3, and MDA-MB-231 cells." (PMID 40906372, 2025). "For example, three loci—MYEOV (rs10737153), TNS1 (rs201030469) and FGFR2 (rs17102399)—have impacts on both PRC layer thickness and risk of diagnosis for breast cancer." (PMID 36848389, 2023). "Breast cancer cells overexpressing TNS1 showed decreased invasiveness, and the knockdown of TNS1 in breast cancer cells increased invasiveness." (PMID 36358270, 2022). "For example, TNS1, as an oncogene, participated in proliferation and invasion in colorectal cancer, while acting as a tumor suppressor in breast cancer cells." (PMID 33269380, 2021). "It has been reported that expression of TNS1 was increased in colorectal cancer, breast cancer and acute myeloid leukemia." (PMID 33269380, 2021). "The general relationship between the expression of Tns1 and different stages/subtypes of breast cancer has been unclear." (PMID 33353933, 2020). "The results of ectopic overexpression or siRNA-mediated knockdown of PURB, resulting in altered expression (upregulation or downregulation, respectively) of Tns1 in 4T1 mammary cancer cells indicating a transcriptional regulatory role of PURB in this context." (PMID 33353933, 2020). "TNS1 also exhibits context-dependent roles in bladder, lung, and breast cancers." (PMID 40906372, 2025). "However, targeted genes of fs-cb-miRs in humans like KLHL20, TNS1, and PAPD4 are associated with Alzheimer’s, malignant tumor of the breast, and hepatitis C virus infection disease, respectively." (PMID 38674383, 2024). "TNS1/miR-548j axis regulates invasion and metastasis of breast cancer cells." (PMID 33231563, 2020). "TNS1 modulated the activation of Cdc42 to regulate cell invasion in breast cancer." (PMID 32190687, 2020). "Low expression of TNS1 promotes metastasis and invasion of prostate cancer and breast cancer cells." (PMID 33231563, 2020). "In addition, Tensin1 (TNS1), a focal-adhesion molecule, is involved in the negative regulation of cell migration, and the reduced expression of TNS1 has been observed in human breast carcinoma, head and neck squamous cell carcinoma." (PMID 31217907, 2019). "Interestingly, both ectopic expression of MaTAR25 or Tns1 in 4T1 MaTAR25 KO cells can rescue the actin filament phenotype, supporting our finding that Tns1 is a critical downstream target of MaTAR25 regulating mammary tumor progression." (PMID 33353933, 2020). "Conversely, TNS1 can suppress migration/invasion: miR-548j enhanced invasion and metastasis of MCF7 breast cancer cells by targeting TNS1 and activating Cdc42." (PMID 40906372, 2025). "Specifically, TOM1L1 and ESR1 were highly expressed, but MAFF, TNS1, EFEMP2, and TRIM31 were significantly downregulated in breast cancer." (PMID 34151731, 2021). "Few targeted genes of fs-cb-miRs like TNS1 (Cte-miR824-3p), UBE2K (Cte-miR168), FNDC3A (Cte-miR6183) and PAPD4 (Cte-miR7780-3p) were involved in malignant tumors of the breast, Alzheimer’s disease, Angelman syndrome and Hepatitis C virus infection, respectively." (PMID 38674383, 2024). "Additionally, the variations in the targeted genes: TNS1, FAM212B and KIAA1549 have led to the diseases such as malignant tumors of the breast, Crohn’s disease and Pilocytic astrocytoma, respectively." (PMID 38674383, 2024).
breast carcinoma (continued). "In addition, downregulation of TNS1, TNS2 or TNS3 reduces the invasiveness of ovarian and breast cancer cell lines by impairing integrin internalization and focal adhesion turnover." (PMID 37510408, 2023). "In summary, miR-548j promotes breast cancer tumor invasion and metastasis but does not affect cell proliferation by inhibiting TNS1 expression, which in turn activates a Rho-GTPase—CDC42." (PMID 36358270, 2022). "TNS1 may promote cell motility and proliferation by mediating signal transduction between the extracellular matrix and actin cytoskeleton and participates in the EMT of cancer cells to promote breast cancer cell proliferation, migration, invasion, and metastasis." (PMID 36358270, 2022).
colorectal cancer (14 papers, 2017 to 2025). A primary or metastatic malignant neoplasm that affects the colon or rectum. "For example, upregulated TNS1 levels increased the risk of mortality in patients with colorectal cancer but were associated with better survival in patients with lung adenocarcinoma." (PMID 37374025, 2023). "More recently, the upregulation of TNS1 in colorectal cancer was found to be associated with poor overall survival in patients, although previous studies have shown suppression of TNS1 expression is associated with metastatic cancers." (PMID 33461601, 2021). "TNS1 was rarely reported to be associated with cancer, but was identified as a potential biomarker in human colorectal cancer and a regulator of metastatic potential in colorectal cancer via altering expression of genes involved in cell motility." (PMID 31866765, 2019). "Moreover, poor survival of patients with colorectal cancer has been associated with elevated levels of transgelin and tensin 1; siRNA of both these proteins decreases proliferation and invasion." (PMID 34203203, 2021). "TNS1 also promotes the progression of colorectal cancer and represents a potential therapeutic target." (PMID 40858565, 2025). "Nevertheless, several recent studies have found that TNS1 has two opposite functions in metastatic and primary colorectal cancers." (PMID 36358270, 2022). "For example, transgelin/TNS1 axis advanced proliferation and invasiveness of colorectal cancer cells." (PMID 33269380, 2021). "Previous bioinformatics analysis indicated that TNS1 was the target of miRNA-31 and associated with the LNM of colorectal cancer." (PMID 34368222, 2021). "In colorectal cancer, TNS1 is identified as a potential biomarker for tumor cell proliferation and invasion." (PMID 33428680, 2021). "It has been reported that upregulated TNS1 accelerates colorectal cancer cellular metastasis." (PMID 37374025, 2023). "TNS1 promotes colorectal cancer cell metastasis and tumor progression." (PMID 36358270, 2022). "Furthermore, elevated tensin 1 expression is a potential biomarker for colorectal cancer, further solidifying pseudophosphatases as therapeutic targets." (PMID 34203203, 2021). "In conclusion, our data demonstrate that the transgelin/TNS1 axis is activated in colorectal cancer, suggesting that it may serve as a potential therapeutic and prognostic biomarker for CRC." (PMID 29416680, 2018). "TNS1 expression is significantly elevated in NSCLC tissues and correlates with poor prognosis, whereas TNS2 mRNA is significantly downregulated in head and neck, esophageal, breast, lung, liver, and colorectal cancers." (PMID 40906372, 2025). "In colorectal cancer (CRC), multiple studies consistently support TNS1’s oncogenic function." (PMID 40906372, 2025). "TNS1, a downstream target gene of miR-31, was lower in primary tumor tissues than in normal tissues, but overall survival (OS) and disease-free survival (DFS) were improved in colorectal cancer patients with low TNS1 expression levels." (PMID 36358270, 2022).
bladder cancer (8 papers, 2019 to 2025). "MicroRNA-mediated downregulation of TNS1 is associated with increased migration, invasion, and metastasis in colon adenocarcinoma, bladder cancer, and lung cancer, supporting its potential tumor-suppressive role in specific contexts." (PMID 40906372, 2025). "The MAGI2-AS3/miR-31-5p/TNS1 axis identified in our study has been shown to regulate migration and invasion ability in bladder cancer cell lines." (PMID 34681112, 2021). "This suggests that EGCG can be a potent adjunctive compound to mitomycin C in bladder cancer treatment through regulating miR-31-5p and its potential target TNS1." (PMID 31805718, 2019). "However, the role of miR-642a-5p in bladder cancer remains unclear, and further investigation is needed to clarify the role of miR-642a-5p-TNS1 interaction in bladder cancer in response to EGCG treatment." (PMID 31805718, 2019). "In bladder cancer (BCa), the lncRNA MAGI2-AS3 targets miR-31-5p to promote TNS1 expression in T24 and J82 cells, inhibiting cell migration and invasion, suggesting a tumor-suppressive role." (PMID 40906372, 2025). "Further functional experiments demonstrated that the MAGI2-AS3/miR-31–5p/TNS1 axis was correlated with advanced tumor stages and lymph node metastasis through the regulation of the migration and invasion of bladder cancer cells." (PMID 36605618, 2023).
prostate carcinoma (6 papers, 2018 to 2025). A carcinoma that arises from epithelial cells of the prostate gland. "TNS1 expression also correlates with bone metastasis of prostate cancer." (PMID 33231563, 2020). "We further identified increased promoter DMR methylation in prostate cancer correlating with decreased expression of mRNA and protein expression also on FBXO2, TGFB1I1, and TNS1." (PMID 29563510, 2018). "Increased gene body methylation in prostate cancer correlating with decreased expression of mRNA and protein expression was identified on GNAO1, LGALS1, TNS1, and PPAP2B." (PMID 29563510, 2018).
lung carcinoma (5 papers, 2019 to 2025). "The downregulation of TNS1 was also demonstrated in two GEO lung cancer datasets, GSE32665 and GSE19188." (PMID 36581942, 2022). "Survival analysis also demonstrated that in patients with lung cancer, high TNS1 expression levels potentially indicated a better prognosis (HR = 0.58)." (PMID 36581942, 2022). "Based on the GEPIA online tool, TNS1 was indicated to be significantly downregulated in both lung cancer subtypes compared with normal tissues." (PMID 36581942, 2022). "Akt/mTOR and RhoA signaling pathway are both critical in lung cancer development, which are reported to be regulated by TNS1." (PMID 33269380, 2021). "In lung cancer, it was found that TNS1 expression was significantly higher in NSCLC tissues and cells than normal." (PMID 33269380, 2021). "TNS1 has been proved to be up-regulated in lung cancer cells following (-)-epigallocatechin-3-gallate treatment which was a potential anticancer agent." (PMID 33269380, 2021). "TNS2 shows promise as a diagnostic adjunct for discriminating GISTs from other gastric sarcomas, while TNS1 and TNS4 are increasingly incorporated into validated multi-gene signatures predicting survival and therapeutic response in bladder, colorectal, gastric, and lung cancers." (PMID 40906372, 2025).
asthma (4 papers, 2014 to 2025). "We found that TNS1 rs918949 was associated with an increased risk of the asthma–eczema phenotype, and gene–environment interaction analyses indicated that both TNS1 and NRXN1 variants conferred the greatest risk among children exposed to ETS in early life." (PMID 41516222, 2025). "Increases in the activity of TNS1 are linked to a risk for the onset of cancer and allergy induced asthma." (PMID 25346719, 2014). "Together, these findings suggest that TNS1 may act as a susceptibility locus predominantly in the context of the combined asthma–eczema phenotype." (PMID 41516222, 2025). "Furthermore, the risk of the eczema-associated asthma phenotype among exposed children carrying the risk alleles fitted a multiplicative model, with ratios of relative risks of 4.70 for TNS1 and 2.16 for NRXN1, respectively." (PMID 41516222, 2025). "Therefore, the present study aimed to investigate the role of SNPs in the NRXN1 and TNS1 genes in susceptibility to atopic eczema and to the eczema-associated asthma complex phenotype in children." (PMID 41516222, 2025). "Moreover, a recent GWAS has identified a SNP in TNS1 with suggestive evidence of its association with asthma and coexisting hay fever." (PMID 26986948, 2016). "Against this background, the observed association of the TNS1 rs918949 variant with the asthma–eczema comorbidity appears biologically plausible, suggesting that genetic variation within TNS1 may modulate barrier-related pathways, particularly relevant in multimorbid allergic disease." (PMID 41516222, 2025). "A key finding of this study is the significant interaction observed between the TNS1 rs918949 and NRXN1 rs10194978 variants and early-life ETS exposure in relation to the asthma–eczema comorbidity phenotype." (PMID 41516222, 2025). "Functional studies further demonstrated that TNS1 regulates α-smooth muscle actin expression and contractile responses in human airway smooth muscle cells, directly implicating this protein in asthma-related airway pathology." (PMID 41516222, 2025). "Synergistic gene–environment interactions were identified for both TNS1 and NRXN1, with the highest risk of the combined asthma–eczema phenotype observed among ETS-exposed carriers of risk alleles." (PMID 41516222, 2025). "To investigate potential gene–environment interactions, we examined the combined effects of early-life ETS exposure and TNS1 and NRXN1 variants on the risk of developing the asthma–eczema phenotype." (PMID 41516222, 2025). "In conclusion, this study provides evidence that genetic variation in TNS1 and NRXN1 may interact synergistically with early-life ETS exposure to increase susceptibility to the combined asthma–eczema phenotype in children." (PMID 41516222, 2025). "In this study, we evaluated whether early-life exposure to ETS interacts with genetic variants at two candidate loci, TNS1 and NRXN1, to impact the development of the combined asthma–eczema phenotype in children." (PMID 41516222, 2025). "Next, we explored whether the early-life ETS exposure interacts with TNS1 and NRXN1 variants to modulate the risk of developing the combined asthma–eczema phenotype." (PMID 41516222, 2025). "Our results are broadly consistent with this concept, as we demonstrate that the TNS1 rs918949 variant is specifically associated with the combined asthma–eczema phenotype but not with eczema alone." (PMID 41516222, 2025). "In this context, it is conceivable that early-life ETS enhances the effect size of the risk alleles at TNS1 and NRXN1, while conversely, these genetic variants may shape the extent to which ETS exposure increases the risk of eczema-associated asthma." (PMID 41516222, 2025). "We aimed to investigate whether variants in TNS1 and NRXN1—previously identified in a genome-wide interaction study—influence susceptibility to atopic eczema and the asthma–eczema phenotype and whether early-life environmental tobacco smoke (ETS) exposure modifies these genetic effects." (PMID 41516222, 2025).
asthma (continued). "Our study provides the first independent replication of these findings in a case-control setting, further supporting the hypothesis that TNS1 and NRXN1 contribute to the susceptibility underlying the asthma–eczema phenotype and that early-life environmental exposures modulate their effects." (PMID 41516222, 2025). "This study resulted in the detection of four new SNPs, among which TNS1 and NRXN1 showed significant evidence for their interaction with ETS exposure in relation to the comorbidity of asthma and eczema." (PMID 41516222, 2025). "Our findings provide the first independent replication of evidence suggesting that TNS1 and NRXN1 may contribute to the asthma–eczema comorbidity through mechanisms that could be substantially modified by early-life ETS exposure." (PMID 41516222, 2025). "In addition, we extended these analyses by evaluating the associations of TNS1 and NRXN1 variants with susceptibility to atopic eczema and to the eczema-associated asthma phenotype in children, irrespective of ETS exposure." (PMID 41516222, 2025). "However, while TNS1 has not been historically associated with any CF phenotype, it has been associated with COPD and asthma lung function." (PMID 34086412, 2021).
colon adenocarcinoma (4 papers, 2020 to 2022). "Survival analysis on GEPIA using colon adenocarcinoma data set screened 5 genes CXCL3, IL1B, IL1A, MET and TNS1 that have significant log rank p value in Kaplan–Meier survival analysis." (PMID 34083590, 2021).